GRPR (gastrin releasing peptide receptor)
Diseases named in the same sentence as GRPR in open-access papers (continued):
Sharing a sentence is not in itself a finding about the gene and the disease.
prostate carcinoma (continued). "Gastrin-releasing peptide receptors (GRPR), G protein-coupled receptors, are another useful target for prostate cancer imaging." (PMID 36765754, 2023). "Before the in vitro affinity study, cytotoxicity of the GRPR-targeted nanobubbles on GRPR+ prostate cancer cells, PC3, was evaluated using Presto Blue cell viability assay." (PMID 36733960, 2023). "GRPR is highly expressed by prostate cancer cells, whereas integrin αvβ3 is expressed by tumor neovasculature." (PMID 36770755, 2023). "The work reported herein demonstrates the ability of GRPR-targeted AuNPs for the specific delivery of Pt(IV) prodrugs to prostate cancer PC3 cells, within an image-guided and theranostic approach." (PMID 36593794, 2023). "To investigate the feasibility of GRPR-targeted ICG nanobubbles as molecular imaging agents, we first tested the GRPR targeting ability of nanobubbles in mouse models of prostate cancer." (PMID 36733960, 2023). "Most relevantly, the 67Ga-labeled AuNP-BBN presented high cellular internalization in human prostate cancer PC3 cells overexpressing the GRPR and a significant tumor uptake in mice bearing prostate cancer xenografts." (PMID 36593794, 2023). "The gastrin-releasing peptide receptor (GRPr) is a molecular target for the visualization of prostate cancer." (PMID 37285007, 2023). "Previous work has shown that in androgen–dependent prostate cancer xenografts, GRPr is highly expressed, but this expression is drastically reduced after castration." (PMID 38201600, 2023). "In their work, Qiu showed that targeted biopsies provided by the combinatorial PET/CT image of PSMA and GRPR PET/CT tracers significantly improved the diagnosis of prostate cancer patients." (PMID 36182995, 2022). "Remarkably, AuNP-BBN has a much higher cellular uptake, being more pronounced in PC3 cells due to its specificity towards the GRPR overexpressed in prostate cancer cells, which is in accordance with previous studies reported for these AuNP platforms." (PMID 35563666, 2022). "For this reason, GRPR analogues have been recently identified as alterative targets for molecular imaging in prostate cancer." (PMID 35053499, 2022). "Radiopharmaceuticals targeting PSMA and GRPR are currently under clinical trials and are being considered as an alternative imaging tool for definitive diagnosis and grading of prostate cancer." (PMID 36182995, 2022). "Another promising target with regard to prostate cancer is the gastrin-releasing peptide receptor (GRPR), which was shown to be overexpressed not only in prostate but also in breast cancer, as well as gastrointestinal stromal tumors, amongst others." (PMID 36145354, 2022). "Our main goal was to promote selective and enhanced radiosensitization of prostate cancers cells based on GRPR-targeted AuNPs." (PMID 35563666, 2022). "Bombesin is a 14-amino acid peptide agonist that binds with high affinity to GRPR and has been shown to increase the motility and metastatic potential of prostate cancer cells." (PMID 36077820, 2022). "Biodistribution studies with the Ga-68/Lu-177-labeled NeoB theranostic pair in mice bearing GRPR-expressing human prostate cancer PC-3 xenografts showed a favorable in vivo stability and high tumor uptake and retention." (PMID 35951084, 2022). "We next extended the preclinical evaluation of the GRPR antagonists to a prostate cancer in vivo model, using male Balb/C nude mice bearing PC3 xenografts." (PMID 36559063, 2022). "68Ga-BBN-RGD targets both αvβ3 and GRPR and thus was tested for its ability to improve the detection rate of primary prostate cancer." (PMID 35311120, 2022). "The peptide was radiolabeled with 67Cu, and specific binding of the radiolabeled peptide towards GRPR-positive PC-3 prostate cancer cells was confirmed with 52.2 ± 1.4% total bound compared to 5.8 ± 0.1% with blocking." (PMID 35745647, 2022).
prostate carcinoma (continued). "The GRPR antagonist 177Lu RM2 has been evaluated in mCRPC patients with high uptake in prostate cancer cells and demonstrates rapid clearance from physiologic GRPR expressing tissues, such as the pancreas." (PMID 36077820, 2022). "The GRPR antagonist [68Ga]Ga-RM2 (RM2=DOTA-4-amino-1-carboxymethylpiperidine-D-Phe-Gln-Trp-Ala-Val-Gly-His-Sta-Leu-NH2) has been particularly attractive for prostate cancer imaging." (PMID 35223907, 2022). "The binding affinities of Ga-TacsBOMB2, Ga-TacsBOMB3, Ga-TacsBOMB4, Ga-TacsBOMB5, Ga-TacsBOMB6, and Ga-RM2 were measured by a cell-based binding assay using GRPR-expressing PC-3 prostate cancer cells." (PMID 35744904, 2022). "A first-in-humans study on 177Lu-RM2 in PSMA-negative/GRPR-positive prostate cancer revealed encouraging dosimetry data." (PMID 35027371, 2022). "Neoplastic cells of human prostate cancer are characterized by the overexpression of both integrin αvβ3 and gastrin-releasing peptide receptor (GRPR)." (PMID 35311120, 2022). "In conclusion, our newly synthesized [44Sc]Sc-NODAGA-AMBA radiopharmaceutical showed excellent binding affinity to GRPR-positive PC-3 prostate cancer cells and tumors." (PMID 36077458, 2022). "Gastrin-releasing peptide receptor (GRPR) has been shown to be overexpressed on many tumors, such as human breast cancer, prostate cancer, colon cancer, and cervical cancer." (PMID 35992794, 2022). "[68Ga]Ga-RM2 was the most clinically tested PET tracer based on this class of GRPR antagonists, studied in a small cohort of healthy volunteers, breast, and prostate cancer patients." (PMID 34830920, 2021). "GRPR signaling is important for the growth, invasion, migration, and progression of prostate cancer, which is the second most commonly diagnosed cancer in men and is the cause of many cancer-related deaths." (PMID 33573232, 2021). "The main aim of this study was to provide a radiotracer that will be simple to radiolabel with 99mTc and to use in clinics for imaging GRPR-overexpressing prostate cancers." (PMID 33573232, 2021). "The radiotracer can be used to image GRPR-overexpressing malignancies, with prostate cancer being the focus, utilizing the wide availability of 99mTc and SPECT worldwide." (PMID 33573232, 2021). "Accordingly, [177Lu]Lu-AMBA was first reported to show high therapeutic potential in several prostate cancer models having different GRPR expression levels, namely based on PC-3, LnCaP, and DU145 cells." (PMID 34830920, 2021). "[68Ga]Ga-RM2 has been widely studied in different prostate cancer cell lines and tumor models and has shown improved binding affinity to the GRPR and metabolic stability." (PMID 34830920, 2021). "The expression of GRPR was found to be higher in the earlier stages of prostate cancer, and this overexpression is androgen-dependent." (PMID 33573232, 2021). "GRPR is overexpressed in various human tumor entities such as BC or prostate cancer and represents a promising target for PET imaging and radionuclide therapy." (PMID 34885214, 2021). "Promising new developments are directed towards bispecific radioligands of PSMA and GRPR to reach maximal detection rates and to capture all prostate cancer lesions." (PMID 34830920, 2021). "Gastrin-releasing peptide receptor (GRPr) imaging is used in the diagnosis of several cancer types, including prostate cancer." (PMID 34358127, 2021). "The wide availability of single-photon emission computed tomography/computed tomography (SPECT/CT) and the generator-produced 99mTc can be utilized to facilitate the use of GRPR-targeting radiotracers for diagnostics of prostate cancers." (PMID 33573232, 2021). "High levels of GRPR-expression have been indeed documented in excised patient biopsy specimens from prostate cancer (PC), especially in its early stages, breast cancer, gastrointestinal stroma tumors and other human cancers." (PMID 34680243, 2021).
prostate carcinoma (continued). "Nevertheless, altogether, the obtained cellular results indicate that both radiocomplexes are mostly taken up by prostate cancer cells through a GRPr-mediated mechanism." (PMID 33467760, 2021). "The first studies regarding the use of GRPRs for PET/CT imaging and treatment of prostate cancer were based on radiolabelled GRPR-agonists, such as 68Ga-AMBA/177Lu-AMBA." (PMID 33809749, 2021). "The dual-targeted complex 99mTc-TPP-BBN is efficiently internalized by human prostate cancer PC3 cells through a specific GRPr-mediated mechanism of uptake." (PMID 33467760, 2021). "The forming [99mTc]Tc-DB15 radiotracer displayed high in vitro uptake in GRPR-expressing mammary (T-47D) and prostate cancer (PC-3) cells." (PMID 34680243, 2021). "In patients with primary prostate cancer, the tracer detected prostate confined pathological lesions with an excellent correlation with GRPR expression status in the excised specimens." (PMID 34830920, 2021). "In particular, understanding the features of GRPR signal in prostate cancer tissue seems critical for improving cancer care, as supported by very preliminary data." (PMID 33854977, 2021). "The designed dual-targeted complex, 99mTc-TPP-BBN, is efficiently internalized by human prostate cancer PC3 cells through a specific GRPr-mediated mechanism of uptake." (PMID 33467760, 2021). "Background: [68Ga]Ga-RM2 is a potent Gastrin-Releasing Peptide-receptor (GRP-R) antagonist for imaging prostate cancer and breast cancer, currently under clinical evaluation in several specialized centers around the world." (PMID 34452121, 2021). "In the present review, we briefly discuss the development of GRPR radioligands, from its early days to its present status, with an emphasis on analogs involved in translational studies in breast and prostate cancer." (PMID 34830920, 2021). "Expression of GRPR in prostate cancer is heterogeneous, dynamic and dependent on the stage of the disease." (PMID 33574368, 2021). "Of particular interest is the final part of this review, in which we present the views of a clinician on the limitations, strengths, and future opportunities in prostate cancer theranostics using GRPR-targeted radiolabeled bombesin analogs." (PMID 34830920, 2021). "The so far attempts to improve the treatment effect of prostate cancer, when using GRPr-analogues, involve dosimetry studies." (PMID 33258012, 2020). "The gastrin-releasing peptide receptor (GRPR) has attracted much attention in nuclear oncology owing to its high-density expression in frequently occurring human cancers, such as prostate cancer, mammary carcinoma, and others." (PMID 32731473, 2020). "The GRPR antagonist [177Lu]Lu-RM2 was studied for the treatment of patients with metastatic castration-resistant prostate cancer by delivering at least one therapy cycle of the GRPR-targeting radioligand." (PMID 33081166, 2020). "Next we tested if GRP/GRPR signaling has an immediate effect on prostate cancer cells with stem cell-like properties." (PMID 32205838, 2020). "Peptide-based radiopharmaceuticals targeting GRPR evaluated in prostate cancer, preclinical, and experimental study models." (PMID 33335885, 2020). "Because of the frequent overexpression of GRPR in prostate cancer, several bombesin radiopharmaceuticals have been tested in humans for PCa disease detection, including [68Ga]RM2, [68Ga]BAY86-7548, and [64Cu]-CB-TE2A-AR06, among others." (PMID 32582550, 2020). "Recent clinical studies have commenced evaluating GRPR antagonists for treating patients with metastatic castration-resistant prostate cancer showing promising results." (PMID 33081166, 2020). "GRPR overexpression in prostate cancer is androgen dependent and is found in 63–100% of primary prostate cancer samples and in more than 50% of lymph node and bone metastases, but not in hyperplastic and benign prostate cells." (PMID 33081166, 2020).
prostate carcinoma (continued). "GRPR is aberrantly overexpressed on the cell surface of many cancers, including lung, breast, and prostate cancer." (PMID 32582550, 2020). "Knockdown or inhibition of GRP receptor (GRPR) delay growth of human prostate cancer xenografts by reducing the pool of cancer-propagating cells." (PMID 32205838, 2020). "In recent years, GRPR has been used as a target for cancer diagnosis and treatment of prostate cancer, breast cancer and small cell lung cancer." (PMID 32651409, 2020). "Overexpression of GRPR is high in the early stages of prostate cancer (but decreases with disease progression when tumors dedifferentiate into higher grade) and in androgen-insensitive and spread metastatic lesions." (PMID 33081166, 2020). "GRPR, a G protein-coupled receptor, has been proven with high expressions on many human tumors, such as prostate cancer, gastrointestinal stromal, breast cancer, ovarian cancer and small cell lung cancer." (PMID 32651409, 2020). "Prostate Specific Membrane Antigen (PSMA) and GRPr are the two receptors, which are overexpressed on the surface of prostate cancer." (PMID 33258012, 2020). "This gastrin-release peptide (GRP) binds specifically to the surface receptors GRPR, which are frequently found in large numbers in prostate cancer." (PMID 33375045, 2020). "Antagonists to GRPR labelled with lutetium-177 were evaluated in preclinical studies on mice bearing prostate cancer xenografts, demonstrating a promising therapeutic efficacy with extended survival of the mice receiving the radiolabelled peptide." (PMID 33081166, 2020). "GRPR is proving to be a good indicator for prostate cancer and is a promising target for molecular imaging." (PMID 33375045, 2020). "Prostate-specific membrane antigen (PSMA) and gastrin-releasing peptide receptor (GRPR) are promising targets for molecular imaging of prostate cancer (PCa) lesions." (PMID 32630176, 2020). "Knockdown or inhibition of GRP receptor (GRPR) abrogate effects of MME deficiency and delay growth of human prostate cancer xenografts by reducing the number of cancer-propagating cells." (PMID 32205838, 2020). "In conclusion, in this study we reported the development of radio-iodinated GRPR/PSMA-targeting bispecific heterodimer [125I]I-BO530 for theranostic applications in prostate cancer." (PMID 31340483, 2019). "Prostate-specific membrane antigen (PSMA) and gastrin-releasing peptide receptor (GRP-R) are expressed in prostate cancer and can be targeted with radiolabeled inhibitors and antagonists." (PMID 31161459, 2019). "Imaging of oligometastatic prostate cancer requires a molecular target that is predominantly expressed in earlier stages of disease such as gastrin releasing peptide receptor (GRPR)." (PMID 31745219, 2019). "The overexpression of GRPR is higher in the early stages of prostate cancers and decreases as the disease progresses." (PMID 31340483, 2019). "For prostate cancer, especially, high-affinity GRPR expression has been identified in tissue biopsy samples and immortalized cell lines." (PMID 31398865, 2019). "Radiolabelled antagonistic bombesin analogues are successfully used for targeting of gastrin-releasing peptide receptors (GRPR) that are overexpressed in prostate cancer." (PMID 31382362, 2019). "A 68Ga-labeled GRPR antagonist (NOTA-PEG3-RM26) was also shown to be a more promising candidate than a 68Ga-labeled agonist (NOTA-Aca-BBN7-14) for imaging of prostate cancer." (PMID 31398865, 2019). "This highlights GRPR as an interesting target for radionuclide therapy of prostate cancer, especially with regards to its low expression in the salivary glands, unlike PSMA, which is known to result in xerostomia." (PMID 30823564, 2019). "The GRPR/PSMA-targeting heterodimer [125I]I-BO530 is a promising agent for theranostics application in prostate cancer." (PMID 31340483, 2019).
prostate carcinoma (continued). "The prostate-specific membrane antigen (PSMA) and gastrin-releasing peptide receptor (GRPR) are identified as important targets on prostate cancer." (PMID 31398865, 2019). "A bombesin-based GRPR antagonist PEGn-RM26 has been extensively evaluated in our group and it was found suitable both for imaging and therapeutic application for GRPR-expressing prostate cancer." (PMID 31340483, 2019). "Considerable efforts have been made in the past decades to target the prostate cancer cell markers GRPR and PSMA." (PMID 31340483, 2019). "The gastrin-releasing peptide receptor (BB2r) is overexpressed in a variety of cancers including prostate cancer." (PMID 31366895, 2019). "Interesting studies evaluated a novel radiolabeled GRPR antagonist, NeoBOMB1, radiolabeled with [67/68Ga/111In/177Lu] as a theranostic tool in a prostate cancer animal model and in prostate cancer patients." (PMID 31652624, 2019). "Thereto, we performed in vivo stability studies, biodistribution studies and SPECT/MR imaging in healthy mice and mice subcutaneously xenografted with the GRPR-expressing prostate cancer cell line PC-3." (PMID 29556947, 2018). "In fact, it has been recently shown that GRPR on prostate cancer cells can be targeted with hybrid elastin-like polypeptide/liposome nanoparticles via a GRP-ELP fusion protein." (PMID 29861840, 2018). "The GRPR is overexpressed at high incidence and high density on various tumors, including prostate cancer, making it an appealing molecule for tumor targeting." (PMID 29556947, 2018). "Most of these research efforts have regarded prostate cancer, given the high density of GRPR since the early phase of neoplastic transformation." (PMID 30543050, 2018). "The gastrin-releasing peptide receptor (GRPR) has been also intensively explored as a target both for imaging or radionuclide therapy of prostate cancer and other GRPR-expressing cancers." (PMID 30583594, 2018). "The first radioactive bombesin analogues successfully used in prostate cancer patients were technetium-labelled GRPR agonists." (PMID 30543050, 2018). "The gastrin-releasing peptide receptor (GRPR) is a G-protein coupled receptor overexpressed in a number of cancer types such as prostate cancer, breast cancer, and gastrointestinal cancer, thereby representing an attractive molecule for tumor targeting." (PMID 29556947, 2018). "This unfavorable result prompted a shift of paradigm in the field of prostate cancer radiopeptides from GRPR-agonists to GRPR-antagonists." (PMID 29137110, 2017). "Highly specific gastrin-releasing peptide receptor (GRPR) targeted NIR-II imaging of prostate cancer in living mice was achieved using the small-molecule probe SCH1100, which represents the first small peptide based NIR-II probe for targeted cancer imaging." (PMID 30034761, 2016). "This approach is mimicked in prostate cancer and breast cancer using bombesin analogs targeting the gastrin-releasing peptide receptors (GRPr) with high affinity." (PMID 26769345, 2016). "In patients with prostate cancer, there is very promising preliminary clinical data pointing to the use of radiolabeled gastrin-releasing peptide receptor (GRP-R) ligands for detecting metastatic disease and monitoring disease progression." (PMID 26897133, 2016). "Antagonists targeting gastrin-releasing peptide receptor (GRPR) are also promising for prostate cancer imaging." (PMID 25687535, 2015). "Gastrin-releasing peptide receptor (GRPR) is known to be overexpressed in several human malignancies, including prostate cancer, and has been implicated in multiple important neoplastic signaling pathways." (PMID 26097883, 2015). "To address the urgent need for early and accurate diagnosis of prostate cancer, we aimed to develop a protein MRI contrast agent capable of monitoring the expression of GRPR." (PMID 26577829, 2015).